KL (klotho)
Diseases named in the same sentence as KL in open-access papers (continued):
Sharing a sentence is not in itself a finding about the gene and the disease.
cancer (continued). "Many studies have found decreased expression of klotho protein in malignant tumors compared with that in normal tissues." (PMID 35666743, 2022). "It was confirmed that klotho expression was decreased in benign mammary gland tumors compared with normal mammary gland tissues and was further decreased in malignant tumors." (PMID 35666743, 2022). "Klotho has also been studied for its potential as a prognostic factor and therapeutic target in cancer." (PMID 35666743, 2022). "In this study, klotho expression in canine mammary glands was investigated and its expression in normal canine breast, benign tumor, and malignant tumor was compared by immunohistochemistry." (PMID 35666743, 2022). "Several previous studies have reported the down-expression of klotho in various human cancers, and much of its mechanism has been revealed." (PMID 35666743, 2022). "Klotho downregulation in cancer seems to be the result of promoter methylation and histone modification." (PMID 34737707, 2021). "It has been reported that the klotho promoter is heavily methylated in many cancers, and is also a function of age." (PMID 34944918, 2021). "Emerging research has also demonstrated a potential therapeutic role for Klotho in cancer biology, which is perhaps unsurprising given that cancer and ageing share similar molecular hallmarks." (PMID 32585905, 2020). "Definitely, further research on pathological derangements of phosphate homeostasis is warranted to uncover the relationship between FGF23/KL dysregulation, disturbed phosphate homeostasis, and cancer development." (PMID 33520985, 2020). "The pleiotropic functions of Klotho have been increasingly recognised, including its importance in relation to tumorigenesis, cancer progression and prognosis." (PMID 32585905, 2020). "For the purposes of this review, we will focus on the effect of alpha-Klotho (referred to as Klotho hereafter) in human malignancies, and discuss its therapeutic potential in the prevention and treatment of cancers." (PMID 32585905, 2020). "Often, cell culture studies revealed similar actions of sKL and overexpression of transmembrane KL in different types of cancer." (PMID 33520985, 2020). "Overexpression of KL or recombinant sKL reduce survival and size of the cancer cell colonies and potentiates chemotherapeutic effects." (PMID 33520985, 2020). "This group demonstrated that overexpression using HA-tagged Klotho via transfection resulted in a reduction of surviving cancer colonies by at least 85% in colorectal HCT-116 and HT-29 cells." (PMID 32585905, 2020). "Klotho, a classical anti‐aging protein, plays critical role in the aging process and in the development of age‐related diseases including cancers." (PMID 31545552, 2019). "Our FFPE clinical specimens revealed decreased Klotho mRNA expression compared to a control, non-cancer kidney tissue." (PMID 29928482, 2018). "The canonical roles of KL in cancer are to inhibit fibrosis and promote metastasis via the TGF, Wnt, IGF-I and the bFGF pathways." (PMID 29884183, 2018). "Numerous studies have shown that KL is frequently downregulated in cancer (gliomas, breast, colorectal, lung cancers, etc.)." (PMID 30441794, 2018). "In consistence with these observations, the physiological role of KL has been widely studied, and demonstrated that KL played negative roles in oncogenesis, progression and metastasis of many cancers." (PMID 29884183, 2018). "Low serum Klotho level was an independent adverse prognostic factor for cancer-specific and progression-free survival in RCC." (PMID 28153033, 2017). "Promoter methylation and histone deacetylation have been found to be epigenetic silencing mechanisms of klotho expression in multiple types of cancer." (PMID 29250031, 2017). "Intriguingly, our data suggest that although Klotho and γKlotho seem to both provide protection against oxidative stress, they have opposite roles in cancer." (PMID 26556877, 2016).
cancer (continued). "Klotho has been identified as an anti-aging gene, and also plays an important role in cancer tumorigenesis, cell survival, differentiation and metastasis." (PMID 25759982, 2015). "Silencing KLOTHO gene expression is mainly mediated through promoter hypermethylation and histone deacetylation in cancer." (PMID 27844013, 2015). "Determination of the role of klotho, progerin and mTOR in colonic carcinogenesis will be a fundamental advance in our understanding of cancer as part of the human ageing process." (PMID 25388238, 2015). "Various studies have observed that promoter DNA hypermethylation contributes to KLOTHO silencing and down-regulation in many cancers." (PMID 27844013, 2015). "Consistent with previous reports in GC and other cancers, restoration of klotho gene expression induced cell cycle arrest and apoptosis in GC cells." (PMID 23432957, 2013). "Klotho was shown to exert an inhibitory effect on the insulin-like growth factor-1 (IGF-1) pathway both in human beast cancer cells and pancreatic cancer cells." (PMID 23437382, 2013). "Further analysis showed that inhibition of PI3K/Akt pathway with specific inhibitor (LY294002) attenuated the promotive effects on cancer growth following interfering with klotho shRNA." (PMID 23437382, 2013). "The function of klotho is very complex, and the signal pathways in cancer development are interwound and cross-linking, so the exact role and working mechanisms of klotho in vitro and in vivo are still waiting to be explored." (PMID 20642846, 2010). "Demethylation and inhibition of specific microRNAs can restore Klotho expression, suggesting that an epigenetic therapeutic approach could be used for some cancers." (PMID 40004457, 2025). "The U-shaped associations between serum Klotho and all-cause and cancer mortality indicate that maintaining an ideal Klotho level in cancer patients could reduce mortality risks." (PMID 40696614, 2025). "Therefore, the effect of prolonged and widespread KL expression should be evaluated, together with a possible interaction with standard cancer treatment regimes." (PMID 40006994, 2025). "However, few studies have systematically examined how cancer status affects the relationship between inflammation and Klotho level." (PMID 40519908, 2025). "In addition, Klotho’s role in enhancing chemotherapy sensitivity and its epigenetic regulation further underscores its potential as a target for cancer treatments." (PMID 40004457, 2025). "Understanding the specific contexts and mechanisms through which Klotho influences different cancers could guide more targeted therapeutic approaches and prognostic assessments." (PMID 41261673, 2025). "Our findings provide further insight into serum Klotho, a longevity hormone, and its nonlinear association with survival outcomes in cancer populations." (PMID 40696614, 2025). "Restricted cubic splines with multiple adjustments showed U-shaped links between serum Klotho and all-cause (P nonlinear = .04) and cancer mortality (P nonlinear = .02)." (PMID 40696614, 2025). "Klotho expression in cancer tissue was found to exhibit at a lower level than the adjacent tissues generally, inversely linked to histological grades and clinical stages, and served as a prognostic marker associated positively with survival in a spectrum of malignancies." (PMID 40696614, 2025). "Moreover, Klotho expression is significantly decreased in malignant tumors, and low Klotho levels are an independent poor prognostic factor for cancer-specific and progression-free survival." (PMID 40134808, 2025). "Two cohort studies in general populations have examined the association between circulating Klotho levels and cancer mortality, with both studies reporting nonsignificant findings." (PMID 40696614, 2025).
cancer (continued). "In this prospective cohort study of 1602 cancer adults, a significant nonlinear association between serum Klotho and mortalities was observed, with identified threshold values of 765.5 pg/mL for all-cause mortality and 767.6 pg/mL for cancer mortality." (PMID 40696614, 2025). "The negative association of serum Klotho with pan-cancer varied significantly based on age, gender and BMI." (PMID 39796185, 2025). "Future research should focus on the precise mechanisms of Klotho’s actions in various cancer types." (PMID 40004457, 2025). "Klotho levels are minimized or silenced in some of the cancers studied in this review." (PMID 40004457, 2025). "Also, its function remains underexplored; more research is necessary to define the action of Klotho in cancer and its functions as a biomarker in cancer." (PMID 40004457, 2025). "Similarly, non-cancer participants exhibited a progressive decrease in Klotho levels across PIV quartiles, with the most substantial reduction observed in Q4 (β = -67.82, 95% CI: -94.34, -41.29, P < 0.0001; P for trend < 0.0001)." (PMID 40519908, 2025). "Additionally, high levels of KL correlate with a better prognosis in various cancers, making it a biomarker for cancer progression and prognosis." (PMID 40004457, 2025). "Given that cancer constitutes a significant contributor to global mortality, with its incidence and impact intensifying with advancing age, unraveling the interplay between α-klotho, frailty, and cancer-related mortality holds paramount importance." (PMID 38602574, 2024). "In addition to IL-10, another protein with anti-inflammatory, antioxidant, and anti-cancer properties involved in cancer biology is known as Klotho." (PMID 38337668, 2024). "This will be helpful to elucidate whether serum Klotho exerts a similar inhibitory effect on cancer as tissue, which may be through its interaction with sex hormones." (PMID 35841322, 2023). "Thus, Klotho insufficiency seems to be involved in human aging and, specifically, in several aging-related diseases, including cancer." (PMID 37681914, 2023). "Besides, we found fewer interaction possibilities in KL than K group, between cancer cells and T cells." (PMID 36871040, 2023). "In summary, our analysis showed that higher levels of serum Klotho were negatively associated with risk of pan‐cancer, but not with cancer‐specific mortality." (PMID 35841322, 2023). "This adds to the growing body of evidence linking Klotho as a new biomarker to cancer and may open new possibilities for cancer diagnosis and treatment." (PMID 35841322, 2023). "Although nonmelanoma skin cancers are a heterogeneous group, Klotho proteins decrease the risk of a variety of cancers likely through shared malignant transformation pathways, allowing us to cluster nonmelanoma skin cancers under 1 category." (PMID 37752937, 2023). "Secreted Klotho inhibits EMT in cancer cells and prevents the spread of cancer." (PMID 37425590, 2023). "Klotho, a gene found on chromosome 13q12, is involved in a variety of processes and signaling pathways in the human body related to vitamin D metabolism; cardiovascular, renal, musculoskeletal, and skin diseases; and cancer biology." (PMID 37425590, 2023). "Whereas, we did not observe any association between serum Klotho level with all‐cause mortality and cancer‐specific mortality (all p > 0.05)." (PMID 35841322, 2023). "The three Klotho proteins have complex roles in different types of cancer." (PMID 37958253, 2023). "Analysis of the survival curve for dogs with malignant tumors revealed that negative klotho expression was significantly associated with poor overall survival and disease-free survival." (PMID 35666743, 2022). "The Klotho gene is often turned off in cancer cells, possibly through a number of mechanisms." (PMID 35903083, 2022). "This study aimed to determine whether klotho is expressed within normal canine mammary glands and whether the expression changes in benign and malignant tumors." (PMID 35666743, 2022).
cancer (continued). "The expression of Klotho is depressed or silenced in almost all types of cancer examined." (PMID 35903083, 2022). "Klotho is also regulated by miRNAs, and this appears to be of importance in cancer." (PMID 35903083, 2022). "This is most evident in fibrosis, inflammation and cancer, which are all countered by Klotho." (PMID 35903083, 2022). "The present study investigated whether klotho is expressed within normal canine mammary glands and whether the expression changes in benign and malignant tumors." (PMID 35666743, 2022). "Some researchers reported that KL levels are epigenetically downregulated in cancer." (PMID 35468874, 2022). "Indeed, multiple studies have shown that Klotho inhibits cancer-cell proliferation, colony formation and invasion; and promotes apoptosis and autophagy." (PMID 35903083, 2022). "Therefore, the molecular mechanisms of Klotho-induced autophagy in cancer need to be further researched." (PMID 34737707, 2021). "Whether targeting KL can be therapeutically exploited in cancer must be investigated in future trials." (PMID 33520985, 2020). "Recently, both Klotho and βKlotho have been reported to be aberrantly expressed in several cancers." (PMID 31681612, 2019). "Interestingly, Klotho has been shown to suppress a range of cancer types 9-12 and its expression is usually downregulated in cancer due to hypermethylation in the promoter region." (PMID 31695781, 2019). "Moreover, Klotho is a regulator of pathways that are commonly altered in cancer and activate MAPK, such as Wnt and FGF." (PMID 30441794, 2018). "Klotho is a single-pass transmembrane protein with documented anti-cancer properties." (PMID 29928482, 2018). "Recent years have witnessed the booming of metabolism reprogramming in cancer cells, thus we questioned whether KL could also participate in metabolism control." (PMID 29884183, 2018). "KL was reported to be involved in the progression of a series of human cancers, including small cell lung cancer, breast cancer, hepatocellular carcinoma, ovarian cancer, and regulating tumorigenesis, proliferation, progression and resistance to traditional antitumor therapies." (PMID 29884183, 2018). "In addition, microRNAs appear to play a role in cancer progression by targeting klotho and regulating its expression." (PMID 29250031, 2017). "Klotho is a novel biomarker involved in aging, cancer, and multiorgan dysfunction." (PMID 28912623, 2017). "KLOTHO also plays a role as a secreted Wnt antagonist, suppressing cancer." (PMID 30460073, 2017). "KLOTHO gene silencing, including DNA methylation, has been observed in some human cancers." (PMID 30460073, 2017). "Since soluble Klotho can inhibit IGF-1, Wnt and transforming growth factor-β (TGF-β) signaling pathways in aging and in certain cancers, whether these pathways are involved in the Klotho-induced regulation of bone formation still needs to be investigated." (PMID 26943181, 2016). "However, as in previous studies, restoration of klotho gene expression was shown to induce both autophagy and apoptosis in two cancer cell types, and an autophagy inhibitor to significantly inhibit klotho-induced cell apoptosis." (PMID 27367669, 2016). "In order to identify whether cell apoptosis is induced in cancer cells with overexpression of Klotho, FACS analysis was used by dural staining with PI and Annexin V-FITC." (PMID 26499380, 2015). "Recent studies have revealed that Klotho plays an important role in cancer tumorigenesis." (PMID 25759982, 2015). "The overexpression of Klotho was previously shown to inhibit cancer cell proliferation and may act as a potential therapeutic strategy in cancers." (PMID 25759982, 2015). "Recently, the relationship of Klotho expression and cancer progression has been studied; however, the role and mechanism in a variety of cancers remain unclear." (PMID 26499380, 2015). "However, evidence regarding the association between serum Klotho and mortalities among cancer survivors is lacking." (PMID 40696614, 2025).
cancer (continued). "However, they did not observe any association between the serum Klotho level with all-cause mortality and cancer-specific mortality." (PMID 39796185, 2025). "Studies have shown that cancer patients commonly exhibit various physiological and metabolic changes, such as increased inflammation, oxidative stress, and reduced renal function, all of which may influence Klotho expression." (PMID 40519908, 2025). "Notably, stratified analyses based on age demonstrated that elevated serum Klotho appeared to be harmful to cancer-specific survival outcomes in individuals aged under 60, indicating that Klotho might exert its effect in an age-specific manner." (PMID 40696614, 2025). "After a median follow-up period of 84.0 months, U-shaped associations between circulating Klotho and all-cause and cancer mortality were observed (P for nonlinear = .04.02, respectively), with identified inflection points (pg/mL) of 765.5 for all-cause and 767.6 for cancer mortality." (PMID 40696614, 2025). "We found Klotho had an inverse effect with risk of pan‐cancer (all p < 0.02), with each unit increase in Klotho (1ug/g creatinine) associated with a 0.9%–2.2% reduction in the risk of cancer, and higher levels showing a stronger negative association (all p‐trend <= 0.0005)." (PMID 35841322, 2023). "Accumulating data suggests that the tissue expression of Klotho proteins and, especially, the detection and quantitation of their soluble forms in body fluids like blood serum may be useful for establishing the diagnosis and prognosis of some types of cancer." (PMID 37958253, 2023). "We found an inverse association between serum Klotho and cancer, but without cancer mortality." (PMID 35841322, 2023). "In addition, we analyzed the quantitative response relationship between serum Klotho and the risk of cancer using RCS, and found no non‐linear relationship (all p > 0.05)." (PMID 35841322, 2023). "Our findings showed that serum Klotho presented a negative association with cancer." (PMID 35841322, 2023). "Therefore, the downregulation of Klotho mediated by p-CS and IS through the DNMT pathway might represent the epigenetic modification explaining the increased risk of cancer in CKD patients." (PMID 37372437, 2023). "Furthermore, Klotho overexpression (KL-OE) reduces the number of cancer cells that survive." (PMID 37425590, 2023). "Therefore, its inhibition by Klotho is relevant to cancer therapy." (PMID 35903083, 2022). "By regulating autophagy, Klotho may also influence the emergence of cancer drug resistance." (PMID 34737707, 2021). "It would be of considerable interest to determine whether progerin levels differ between normal versus neoplastic human colonic tissues, and whether different Klotho gene variants are associated with altered CRC risk and/or with the age at which cancer is diagnosed." (PMID 25388238, 2015). "Conversely, in pancreatic cells, Klotho expression inhibits ERK1/2, which contributes to the downregulation of cancer cell proliferation." (PMID 40004457, 2025). "There is also evidence suggesting that Klotho can function as a co-receptor for FGF19; this mechanism involves using different pathways to influence the progression of cancer cells." (PMID 40004457, 2025). "Furthermore, it has become evident that Klotho could have a role in the progression of cancer." (PMID 40004457, 2025). "Moreover, studies have confirmed that Klotho is a multifunctional protein that can inhibit inflammation, resist cancer and regulate the endocrine system, which may further accentuate the potential of Klotho to be the ideal molecule in inducing bone restoration clinically." (PMID 39465174, 2024). "Klotho can suppress cancer by inhibiting IGF-1 signaling, which is known to be upregulated in cancer cells and promotes cancer growth and metastasis." (PMID 35666743, 2022). "It is epigenetically silenced in cancer, and both klotho and KL1 reduce growth of cancer cells in vitro and in vivo." (PMID 34944918, 2021).